SYTL4 (synaptotagmin like 4)
Description:
Modulates exocytosis of dense-core granules and secretion of hormones in the pancreas and the pituitary. Interacts with vesicles containing negatively charged phospholipids in a Ca(2+)-independent manner (By similarity).
Synonyms: Slp4
Tractability: Antibody: its Gene Ontology location is reachable by antibodies, with high confidence; UniProt places it where antibodies can reach, with medium confidence. PROTAC: ubiquitination databases record sites on it; its protein half-life has been measured.
Gene: Protein-coding gene on chromosome X (100,671,783 to 100,732,151, reverse strand). Ensembl gene ENSG00000102362.
Subcellular location: Membrane; Cell membrane; Cytoplasmic vesicle, secretory vesicle membrane
Subcellular location (Human Protein Atlas): Vesicles
Pathways (Reactome):
Hemostasis: Platelet degranulation
Gene Ontology:
Molecular function: protein binding; neurexin family protein binding; phospholipid binding; AP-3 adaptor complex binding; small GTPase binding
Biological process: lysosome localization; multivesicular body sorting pathway; plasma membrane repair; positive regulation of exocytosis; positive regulation of protein secretion; regulation of plasma membrane repair; exocytosis; intracellular protein transport
Cellular component: endosome; exocytic vesicle; plasma membrane; platelet alpha granule membrane; membrane; secretory granule; transport vesicle membrane
Homologues: Orthologues: chimpanzee SYTL4 (100% identical), macaque TSPAN6 (99% identical), dog SYTL4 (94% identical), pig SYTL4 (93% identical), rabbit SYTL4 (93% identical), rat Sytl4 (92% identical), guinea pig SYTL4 (91% identical), mouse Sytl4 (91% identical), tropical clawed frog sytl4 (61% identical), zebrafish sytl4 (50% identical). Paralogues in human: SYTL5 (42% identical), SYTL2 (32% identical), SYTL3 (30% identical), SYTL1 (28% identical), RPH3A (20% identical), SYT10 (17% identical), SYT3 (17% identical), SYT6 (17% identical), SYT7 (17% identical), SYT5 (16% identical), SYT9 (16% identical), DOC2B (16% identical), and 19 more.
Diseases named in the same sentence as SYTL4 in open-access papers:
SYTL4 is named in the same sentence as 26 diseases in open-access papers, as found by Europe PMC text mining. Sharing a sentence is not in itself a finding about the gene and the disease. The quoted sentences say what the papers report.
breast carcinoma (5 papers, 2016 to 2026). "Furthermore, high levels of SYTL4, as in our case study, are associated with a poor prognosis for breast cancer." (PMID 34715892, 2021). "Herein, it is shown that SYTL4 mRNA expression is significantly (p = 2.01 × 10-4) diminished in breast cancer bearing BRCA1 mutations, suggesting a mechanistic interplay between BRCA1-driven genomic instability and SYTL4-regulated signaling cascades." (PMID 42196512, 2026). "To explore the phenotype of SYTL4-mediated resistance in vitro and in vivo, we first evaluated SYTL4 expression across breast cancer cell lines in publicly available data (GSE58135)." (PMID 33042263, 2020). "It would also be interesting to investigate why SYTL4 is highly expressed in TNBC tumors but not in other breast cancer subtypes." (PMID 33042263, 2020). "Within public breast cancer cohorts that underwent NAC, SYTL4 was also highly expressed in non-pCR patients (GSE22513) and upregulated in post-NAC samples (GSE32603)." (PMID 33042263, 2020).
autism (3 papers, 2019 to 2023). Persistent deficits in social interaction and communication and interaction as well as a markedly restricted repertoire of activity and interest as well as repetitive patterns of behavior. "Our analysis of 298 validated/predicted microRNA interactions with mouse Sytl4 gene has identified three of five autism-associated serum miRs (60%), namely, miR181b-5p, miR320a, and miR130a-3p, which have good predictive power in serum." (PMID 31323913, 2019). "Moreover, in recent studies, disturbed SYTL4 gene function has been associated with neuropsychiatric disorders, such as autism, schizophrenia and depression as well as the immune system." (PMID 31323913, 2019). "The SYTL4 gene’s molecular functions, biological processes and molecular pathways are indicative of its significant role in neuronal function that is meaningful in the causation of high-functioning autism in our proband." (PMID 31323913, 2019). "A study (reported by our co-authors: SKR, MGB) in whole exome sequencing in females with autism, a non-synonymous missense mutation (X: 99941091; C>G; p.H448D) of the SYTL4 gene was observed in a female with autism and random X-chromosome inactivation (46–54%)." (PMID 31323913, 2019). "Therefore, the defect in the RAB protein-binding region in the N-terminal half of the SYTL4 protein is due to the R C amino acid variant and may be a causal factor for the high-functioning autism in our patient." (PMID 31323913, 2019). "Research findings will be discussed that relate specifically to SYTL4 and TMEM187 gene variants seen in our patient and as emerging candidate genes for autism." (PMID 31323913, 2019). "Sytl4 is most likely a candidate gene for autism, but thus far, has no known association with cardiac impairment." (PMID 37221250, 2023). "A missense mutation in SYTL4 was also recently reported in a female with autism and non-skewed X-chromosome inactivation." (PMID 31323913, 2019).
autism spectrum disorder (3 papers, 2019 to 2024). A spectrum of developmental disorders that includes autism, and Asperger syndrome. "We describe a 7-year-old male with high-functioning autism spectrum disorder presenting for genetic services and whole exome sequencing following a normal microarray analysis, and variants were found in two X-linked genes: SYTL4 and TMEM187." (PMID 31323913, 2019). "Notably, IGKC, known for its role in immunological and cancer-related processes, along with TMEM187 and SYTL4—genes associated with autism spectrum disorders—show interactions with key genes in these areas." (PMID 38778304, 2024). "TMEM187 and SYTL4 genes have been found to interact directly with known autism spectrum disorder genes, with their mRNAs present in extracellular vesicles in the nervous system, facilitating the translation of active proteins in target cells." (PMID 37710308, 2023). "Our research findings will be discussed related specifically to both the SYTL4 and TMEM187 gene variants seen in our patient and evidence for the two gene variants playing a role in the causation of high-functioning autism spectrum disorder." (PMID 31323913, 2019). "The SYTL4 gene is known to directly interact with several members of the RAB family of genes, such as, RAB27A, RAB27B, RAB8A, and RAB3A which are known autism spectrum disorder genes." (PMID 31323913, 2019).
triple-negative breast carcinoma (2 papers, 2020 to 2022). An invasive breast carcinoma which is negative for expression of estrogen receptor (ER), progesterone receptor (PR), and human epidermal growth factor receptor 2 (HER2). "It has been postulated that SYTL4 confers resistance to paclitaxel in triple-negative breast cancer." (PMID 35747825, 2022).
Anxiety (1 paper, 2019). Intense feelings of nervousness, tension, or panic often arise in response to interpersonal stresses. "In a mouse model of anxiety, significant change in Sytl4 was observed among the altered protein networks in the brain proteome." (PMID 31323913, 2019). "In addition, in a mouse model of anxiety, significant changes in Sytl4 were observed among the altered protein networks in the brain proteome." (PMID 31323913, 2019).
ischemia (1 paper, 2007). A hypoperfusion of the BLOOD through an organ or tissue caused by a PATHOLOGIC CONSTRICTION or obstruction of its BLOOD VESSELS, or an absence of BLOOD CIRCULATION. "We also performed immunohistochemistry on one gene regulated in both sham and ischemia (Sytl4), and confirmed the distribution preference to CA3." (PMID 17937787, 2007).
major depressive disorder (1 paper, 2019). An episode of depression lasting two or more weeks without an intervening episode of mania. "SYTL4 expression is down regulated in the dorsal raphe nucleus from patients with major depressive disorder." (PMID 31323913, 2019). "The SYTL4 gene expression is down regulated in the dorsal raphe nucleus of patients with major depressive disorders." (PMID 31323913, 2019).
nasopharyngeal carcinoma (1 paper, 2023). A carcinoma arising from the nasopharyngeal epithelium. "In nasopharyngeal carcinoma, LMP-1 increases the packaging of hypoxia-inducible factor 1α (HIFα) into EVs and the secretion of EVs through syndecan-2 (SDC2) and synaptotagmin-like-4 (SYTL4)—NFκB pathway." (PMID 36674550, 2023).
Obesity (1 paper, 2024). Accumulation of substantial excess body fat. "Diagnostic value evaluation by ROC analysis determined Sytl4 and Kncn2 as hub genes for maternal obesity in the offspring." (PMID 38544384, 2024). "Our study systematically identified two candidate hub genes (Sytl4 and Kcnc2) and developed a nomogram for diagnosing the obesity‐associated risks in offspring through various bioinformatics analyses and machine learning algorithms." (PMID 38544384, 2024). "This study identified two candidate hub genes (Sytl4 and Kcnc2), developed a nomogram for diagnosing the obesity‐associated risks in offspring and presented a dysregulated proportion of immune cells in the hypothalamus of offspring due to maternal obesity." (PMID 38544384, 2024). "Using integrated bioinformatics analysis and machine learning methods, we identified two hub genes (Sytl4 and Kcnc2) and developed a nomogram to assess obesity risk in offspring exposure to maternal obesity." (PMID 38544384, 2024). "Two candidate hub genes (Sytl4 and Kcnc2) were identified and a nomogram was developed to predict obesity risk in offspring with maternal obesity." (PMID 38544384, 2024). "Here, through integrated bioinformatics analyses and machine learning methods, we identified two pivotal immune‐associated candidate genes (Sytl4 and Kcnc2) and constructed a nomogram for diagnosing the obesity‐associated risk in the offspring of mothers with obesity." (PMID 38544384, 2024). "The in vivo HFD‐induced obesity model and the in vitro PA‐induced microglial inflammation model both verified the increased expression of Sytl4, indicating its potential role in hypothalamic inflammation in obese offspring." (PMID 38544384, 2024).
schizophrenia (1 paper, 2019). A major psychotic disorder characterized by abnormalities in the perception or expression of reality. "Fifty percent (4/8) of the ASD-associated miRs (miRs106, miRs130a, miRs181b, and miRs328) that are predicated to interact with the mouse Sytl4 gene are also known to be associated with schizophrenia, supporting the contention that ASD and schizophrenia share common neurobiological features." (PMID 31323913, 2019).
cancer (6 papers, 2020 to 2026). A tumor composed of atypical neoplastic, often pleomorphic cells that invade other tissues. "Mutation-driven regulation of SYTL4 expression, treatment response to trastuzumab, cancer hallmark enrichment, and survival associations were evaluated using established bioinformatic tools and enrichment analysis based on integrated cancer hallmark gene sets." (PMID 42196512, 2026). "SYTL4 mediates CXCL8 secretion from gemcitabine-resistant cancer cells; therefore, we further examined its role in fibroblast–glutamine exchange." (PMID 41444422, 2025). "Among them, five genes (FGG, MYH15, STARD4, SYTL4, and TMEM267) were first associated with cancer procession, while the other three (KRT81, KRT6A, and KRT13) have previously been confirmed to be related to cancer metastasis and migration." (PMID 37817112, 2023). "In addition, we identified SYTL4 as a new microtubule destabilizer, enabling a better understanding of the regulatory mechanisms of microtubule dynamics in cancer cells." (PMID 33042263, 2020). "Moreover, SLC6A14 induced CXC motif chemokine ligand 8 secretion via synaptotagmin-like 4-mediated exocytosis, paracrinally activating CXCR2 signaling in cancer-associated fibroblasts to enhance mitochondrial fission and amino acid recycling, supporting PDAC progression." (PMID 41444422, 2025). "It has been recently shown that LMP1 promotes EVs secretion and may enhance cancer progression and metastasis by up-regulating syndecan-2 (SDC2) and synaptotagmin-like-4 (SYTL4) through nuclear factor (NF)-κB signaling." (PMID 32521696, 2020).
tumor (4 papers, 2020 to 2025). "SYTL4 expression was markedly higher in gemcitabine-resistant PDAC tumor tissues than in normal and gemcitabine-sensitive tissues." (PMID 41444422, 2025). "Recently, LMP1 has been shown to enhance EV release through Syndecan-2 and synaptotagmin-like-4 through NF-κB signaling and this promotes cell proliferation, invasion and tumor growth in vivo." (PMID 33382850, 2020). "SYTL4 was highly expressed in a cluster of epithelial tumor cells, which were enriched in metabolic-related pathways." (PMID 33042263, 2020). "Meanwhile, knocking down SYTL4 in organoids improved the tumor sensitivity to paclitaxel, suggesting that SYTL4 may serve as a potential therapeutic target for paclitaxel resistance in TNBC." (PMID 33042263, 2020). "In addition, high SYTL4 expression correlated with myogenesis, EMT, apical junction and angiogenesis, suggesting a possible role of SYTL4 in the tumor microenvironment, which needs further assessment." (PMID 33042263, 2020). "Furthermore, silencing SYTL4 enhanced sensitivity to paclitaxel in the BALB/c nude mouse model without affecting tumor growth." (PMID 33042263, 2020).
neurological disorders (2 papers, 2019 to 2021). "Targeted null/knockout mice mutant in SYTL4 phenotypes showed abnormal behavior and neurological disorders." (PMID 34445777, 2021).
heart disease (1 paper, 2023). "Although one (Gatb) has already been linked to heart disease in the literature, the other three phenotypes (Cnot6l, Slc6a15, Sytl4) describe novel findings worth further exploration." (PMID 37221250, 2023).
metabolic disorders (1 paper, 2024). "In this study, we identified Sytl4 as a hub gene for metabolic disorders in the offspring of obese mothers." (PMID 38544384, 2024).
SYTL4 also shares sentences with these, for which no sentence is quoted: bipolar disorder (1 paper); depression (1); epilepsy (1); Epileptic encephalopathy (1); inflammation (1); Intellectual disability (1); Macrocephaly (1); overnutrition (1); panic disorder (1); pheochromocytoma (1); type 2 diabetes (1).